SMAD4 (SMAD family member 4)
Diseases named in the same sentence as SMAD4 in open-access papers (continued):
Sharing a sentence is not in itself a finding about the gene and the disease.
tumor (continued). "SMAD4 participates in SMAD4-dependent TGF-β signalling, which is common during tumour development and progression, and it might act as a tumour suppressor by inhibiting cell proliferation." (PMID 32616892, 2020). "It needs to be further investigated whether defects in SMAD4 O-GlcNAc antagonize TGF-β-induced EMT, tumor migration, or invasion in various cancer cells." (PMID 33199824, 2020). "Smad4 can directly bind to the E-cadherin gene (CDH1) promoter and inhibit its transcription, and its expression can enhance the tumor cells’ resistance to apoptosis and ability to survive various stress conditions, which leads scholars to recognize it a key protein to control EMT." (PMID 32897241, 2020). "Based on our results, we propose that B3GNT3 overexpression, SMAD4 inactivation, and KRAS activation may interact to promote tumor growth and inhibit the infiltration of CD8+ T cells in PC." (PMID 33316775, 2020). "In contrast, tumours with low Smad4 expression would not be expected to exhibit robust EMT reversal due to Slug upregulation is this molecular context." (PMID 31481735, 2019). "Notably, SMAD4 is a downstream effector of transforming growth factor β (TGF-β), a cytokine with tumor suppressive activity." (PMID 31160676, 2019). "Smad4, as the common-partner Smad, is a pivotal mediator of transforming growth factor-β (TGF-β) signaling pathway and could play a significant role in tumor invasion and metastasis." (PMID 30617054, 2019). "Interestingly, our results reveal a down-regulation of TGFβ1 and an up-regulation of TGFβ2, TGFβ3, Smad4 and RAC1b in treated cells, suggesting that PRP treatment promotes the TGFβ pathway role via a tumour suppressive route." (PMID 31388092, 2019). "The aberrant expression of SMAD4, including genetic alterations or homozygous deletion, can directly alter the normal signalling of the TGF-β pathway and lead to uncontrolled cell growth and tumour induction in the pancreas." (PMID 31684910, 2019). "Of note, all cells expressed comparable levels of Smad4, indicating that this master tumor-suppressor gene was not deleted during PDAC development of the donor mice." (PMID 31171768, 2019). "For example, it was found that as a consequence of promoter hypermethylation, the relative expression of the SMAD4 gene was significantly lower in the tumours of LC-IPF patients compared to those who had LC without IPF." (PMID 30704051, 2019). "Immunohistochemical analysis of 637 ccRCC tissue samples revealed a negative correlation between expression of SMAD3 and SMAD4, and the age of patients, nuclear grade, tumor size, as well as pTNM stage." (PMID 31842336, 2019). "Negative SMAD4 expression showed a significant relationship with tumour diameter (χ2 = 6.389, P = 0.016), TNM staging (χ2 = 6.303, p = 0.016), lymphatic invasion (χ2 = 74.451, P = 0.000) and differentiation (χ2 = 5.272, P = 0.039)." (PMID 31684910, 2019). "In addition, SMAD family member 4 (Smad4) and glycine-N-methyltransferase (GNMT) were described among miR-224 target genes, and their involvement in liver injury and tumor progression was proved by in vitro and in vivo models." (PMID 31805631, 2019). "However, the low expression of Smad4 was able to reduce the inhibitory effect of TGF-β1, which promoted the growth of CC tumor." (PMID 31143092, 2019). "SMAD4 is a vital molecule in the TGF-β pathway, which has broad effects on tumour pathology." (PMID 31684910, 2019).
tumor (continued). "Smad4, one of the key mediators of TGF-β signaling, is recognized as global tumor suppressor." (PMID 31238579, 2019). "However, the addition of VPA dramatically upregulated histone H3 acetylation, increased the sensibility of AKT and inhibited pSMAD3/SMAD4, letting the combination of VPA and metformin remarkably reappear the anti-tumour effects of metformin in 786-M-R cells." (PMID 29665787, 2018). "Although additional future studies are needed to identify the detailed mechanism, our results indicated that SIRT7 suppressed the EMT in OSCC metastasis by promoting SMAD4 deacetylation, which constitutes an important insight into the role of SIRT7 in tumor metastasis." (PMID 30001742, 2018). "Reassuringly, the resulting list includes several known colon tumor suppressors such as APC, TCF7L2, MCC, PTEN, and SMAD4." (PMID 29196508, 2017). "Importantly, SMAD4, SMAD3, and other key components of the TGF-β/SMAD signaling pathway (i.e., TGFβr1, TGFβr2, and SMAD2) are found within exosomes isolated from tumor cell lines and from human plasma samples." (PMID 28060758, 2017). "SMAD4 is the pivotal factor of the TGF-β pathway and functions as a key tumor suppressor." (PMID 28055015, 2017). "Thus, cyclin D1 physically and functionally interacts with pSmad2/3 and Smad4 in both HCC cells and HCC primary tumor tissues, which further implicates in the pathogenesis of the disease, such as a poor prognosis for HCC patients." (PMID 28415588, 2017). "In consideration of tumor heterogeneity, we have not found KRAS, CDKN2A or SMAD4 mutations in our samples." (PMID 28008139, 2017). "Moreover, SMAD4 loss might underlie a more aggressive tumor pattern not only because tumor cells acquire a pro-proliferative and pro-metastatic phenotype, but also because it might create a favorable soil for tumor growth and metastasis by conditioning the surrounding stroma." (PMID 29156694, 2017). "SMAD4, which lies downstream of SMAD2/3, is known to be an important tumor suppressor." (PMID 28417919, 2017). "Two of these patients (patients 037 and 045) had an APC variant detected in the primary tumour but not in the PM sample whilst for the third patient (patient 051) PIK3CA, AKT1 and SMAD4 mutations were detected in the primary tumour but not in the PM sample." (PMID 29029407, 2017). "There was no significantly difference of SMAD4 protein loss rate between large and small size of PDCA tumor, OR was 0.94 with 95% CI 0.70-1.25, z=0.42, p=0.68, I2=0%." (PMID 28053288, 2017). "SMAD4 loss was detected in 92 pts (64%); patient characteristics such as gender, age, tumor grading, disease stage or number of metastatic sites had no significant impact on tumoral SMAD4 status." (PMID 28534865, 2017). "SMAD4 is a pivotal member of the TGF-β signaling pathway and functions as a tumor suppressor." (PMID 29065177, 2017). "Reduced SMAD1 and SMAD4 expression was seen across all cancer subtypes, but SMAD5 was differentially expressed: it was downregulated in canonical tumours (n = 149), but was retained and modestly upregulated in poor‐prognosis, mesenchymal tumours (n = 78)." (PMID 28299802, 2017). "The TGF-β pathway was deregulated by alterations to TGFBR1, TGFBR2, ACVR2A, ACVR1B, SMAD2, SMAD3 and SMAD4 in 27 % of non-hypermutated MSS tumours and 87 % of hypermutated cancers." (PMID 27325016, 2016).
tumor (continued). "Interestingly, five genes with concordance between CNLs and down-regulation were observed in more than 50 tumor samples, including MTAP (216 samples), PTEN (143 samples), MCPH1 (86 samples), SMAD4 (63 samples), and MINPP1 (51 samples)." (PMID 27929028, 2016). "In a genetically-engineered Apc+/∆716/Smad4+/− compound knockout mice that develop invasive intestinal adenocarcinomas, mouse CCL9 (mCCL9) is secreted from the cancer epithelium, which recruits CCR1+ myeloid cells to promote tumor invasion." (PMID 27136535, 2016). "The downstream activation of SMAD3 did not involve regulation of SMAD4, as expression levels of this protein did not change in any treatment nor in xenograft nor in 3D-cultured tumor cells." (PMID 26956045, 2016). "In PDAC tissue microarray, a significantly inverse correlation between miR-301a-3p ISH scores and SMAD4 IHC scores were observed in both tumor and corresponding non-tumor tissues." (PMID 26019136, 2015). "Last but not the least, in tumor xenograft samples and clinical samples IHC analysis, enforced miR-301a-3p overexpression triggered a repressive effect on endogenous SMAD4 protein expression." (PMID 26019136, 2015). "Positive staining of Smad4 was mainly identified in the cell cytoplasm of cancer cells in 18 of 27 tumor tissues and negative staining for Smad4 protein in 5 of 7 NBD tissues." (PMID 26077733, 2015). "SMAD4 has been documented in a large number of cancers, including PDAC, in which this gene was more likely considered as a kind of tumor suppressor in tumor growth, metastasis and relapse." (PMID 26019136, 2015). "Also consistent with the CGP results is lapatinib’s (row-clade d) sensitivity to tumor cells with ERBB2_MUT (column-clade E), which, according to these results, is also accompanied by MUTs in CCND1, NF2 and SMAD4." (PMID 26132924, 2015). "In in vitro and in vivo experiments, adding TGF-β to SMAD4-null cell lines resulted in increased proliferation rather than tumour suppression." (PMID 24393789, 2014). "Although most attention has focused on the cell cycle arrest mediated by TGF-β1/SMAD4 signaling, the other tumor suppressive effects of SMAD4 in preventing late stage tumor progression are still not fully understood." (PMID 24625091, 2014). "In univariate analyses, lymph node positivity, surgical margin positivity, non-localized tumor, age at prostatectomy, and biomarkers CCND1, HMMR, IGF1, MKI67, SIAH2, and SMAD4 in malignant epithelium were significantly associated with time to BF." (PMID 24708576, 2014). "Various studies have proposed potential SMAD4-mediated anti-tumor effects in human malignancy; however, the relevance of SMAD4 in the PDAC molecular phenotype has not yet been fully characterized." (PMID 24625091, 2014). "Advanced human cancer cells that retain TGF-β/SMAD signaling but lack tumor suppressive responses can make use of the SMAD pathway to their advantages, and via SMAD3/SMAD4 stimulate pro-invasive and pro-metastatic target genes (for example, IL11, CTGF, CXCR4) and reprogram (EMT) phenotypes." (PMID 24756567, 2014). "Here, we report that re-expression of SMAD4 in SMAD4-null PDAC cells does not affect tumor cell growth in vitro or in vivo, but significantly enhances cells migration in vitro." (PMID 24625091, 2014).
tumor (continued). "miR-34a was also reported to target Notch signaling pathway to inhibit tumor stem cell invasion by directly binding to NOTCH1, DLL1 and JAG1 as well as Wnt signaling pathway by targeting WNT1 and WNT3 genes and TGF-β signaling pathway via Smad4." (PMID 23823624, 2013). "We proceeded to evaluate the clinical relevance of our experimental observation by examining the expression of miR-224 and SMAD4 in the tumor and paired adjacent non-tumorous tissues from 100 HCC patients." (PMID 23922662, 2013). "Since several key genes in the pathway were overexpressed in tumor tissues, including TGFB2, TGFBR1, SMAD2, and SMAD4, TGFβ signaling pathway may be involved in the pathogenesis of fibroblastic meningioma." (PMID 23285163, 2012). "Most normal tissue showed strong to moderate Smad4 immunoreactivity (24/25, 96%), whereas most tumor tissue showed absent (10/25, 40%) or weak (10/25, 40%) immunoreactivity for Smad4." (PMID 22195733, 2011). "In addition, PTEN, SMAD4, and NOTCH1, are known tumor suppressors whose transcript or protein levels are decreased in tumors." (PMID 19922656, 2009). "The results of our study, performed in normal rather than tumor cells where additional (epi-) genetic alterations may confound the analysis, are relevant for our understanding and elucidation of the initial steps underlying SMAD4-driven intestinal tumorigenesis." (PMID 19014666, 2008). "Low and high Smad4 expression levels were retained in vivo, as confirmed in Northern blots of tumour-derived mRNA (data not shown)." (PMID 17997817, 2007). "It has previously been demonstrated for other tumor suppressors as well, e.g. PTEN and Smad4." (PMID 17941976, 2007). "In this study, lymph node negative cases were matched for T-classification, tumour depth and tumour location and demonstrated a statistically significant difference (P=0.024) in Smad4 protein expression level between liver-metastasis (+)/(−) groups." (PMID 17088901, 2006). "Applying the IRS criteria, 23% of the tumor tissues were Smad4-negative (IRS = 0), and a further 41 % stained weakly positive (1 ≤ IRS ≤ 3)." (PMID 16438724, 2006). "There was no significant change in the intracellular localization of Smad4 in the tumor tissues as compared to the surrounding normal epithelium (data not shown)." (PMID 16438724, 2006). "Three candidate tumour suppressor genes, DCC, SMAD4 and SMAD2, map to this region." (PMID 10993648, 2000). "Importantly, the liver-specific cytostatic effect of Smad4 reactivation was confirmed in the GEMMs, where short-term (7-day) Smad4 restoration reduced the percentage of Ki67+ tumor cells in liver metastases but not in primary tumors or lung metastases." (PMID 40999053, 2025). "To study Smad4 reactivation in metastatic tumors, we turned to transplantation assays using cell lines derived from primary GEMM tumors that were capable of metastasis, as this approach afforded longer experimental time before tumor burden necessitated mouse euthanasia." (PMID 40999053, 2025).
tumor (continued). "Thus, Klf4 and Runx1 depletions are sufficient to reverse and blunt Smad4 function in liver and lung metastases, respectively, which demonstrates that KLF4 facilitates Smad4’s tumor-suppressive activity in the liver and RUNX1 contributes to Smad4’s tumor-promoting activity in the lungs." (PMID 40999053, 2025). "Hence, we speculate that the METTL3/miR-146a-5p/SMAD4 axis could serve to facilitate this switch in OSCC, thereby converting the tumor-suppressive properties of TGF-β signaling into tumor-promotive capabilities." (PMID 40338154, 2025). "Notably, SMAD4 mutations were absent in H/L patients but present in 0.8% of NHW patients, which is consistent with prior studies suggesting its role as a tumor suppressor frequently altered in HCC." (PMID 40282485, 2025). "The tumor promoting effect of BMP4 is potentially mediated by SMAD4-independent non-canonical signalling that leads to accelerated DNA replication and cell cycle progression, which needs to be considered if patients with SMAD4-low/null tumors were to receive therapies that activate BMP signalling." (PMID 38689334, 2024). "Hence, the collaboration between RAC1b and TAp73 in suppressing EMT and cell motility might extend to other tumor-suppressive modes of TGF-β; for instance, a SMAD4-dependent lethal form of EMT." (PMID 38255305, 2024). "Interestingly, Smad4 promoted nuclear translocation of activating transcription factor 3 (ATF3) to activate the p38 mitogen-activated protein kinases signaling pathway by binding to ATF3, inducing apoptosis of neuro-2a cells and inhibiting tumor growth." (PMID 38218852, 2024). "Similarly, Smad4 deletion in S100A4+ cells down-regulated the expression of M1-like factors such as iNOS and IL-12 and up-regulated the expression of M2-related genes such as Arg1 and IL-10 in CRC tumor tissues." (PMID 39664586, 2024). "The deletion of Smad4 may not just initiate tumors, but could also act as a factor that promotes tumor metastasis in gastrointestinal cancers." (PMID 38780677, 2024). "However, given the role of Smad4 in genomic stability and tumor suppression, tumorigenesis in the Smad4 KO chronic DSS mouse model is not surprising, especially in the presence of a DNA-damaging agent such as AOM (azoxymethane)." (PMID 39366762, 2024). "Furthermore, to reveal mechanisms by which BMP4 regulates tumor progression in the presence and absence of SMAD4, we have completed transcriptomic analyses of the canonical and non-canonical signalling pathways that are modulated by BMP4." (PMID 38689334, 2024). "Ying Zhang’s studies at National Institutes of Health (USA) proposed that the presence or absence of Smad4 may dictate the outcome of TGF-β signaling toward tumor progression." (PMID 38780677, 2024). "In addition, we still cannot explain why BMP4 acts to drive tumor progression in some other cancer types, since SMAD4 status appears to not be the major factor." (PMID 38689334, 2024). "Through both univariable and multivariable analyses, we also revealed that high CDKN2A and SMAD4 mutation abundances in ctDNA but not in tumor and high ARID1A mutation abundances in both ctDNA and tumor at baseline and/or the second measurement were linked to inferior OS and/or PFS." (PMID 38378604, 2024). "It was observed that the protein expression of Smad4 in NKp46+NK cells at 8 weeks (Wk 8) was significantly decreased compared to that at 4 weeks (Wk 4).When analyzed collectively, we observed a widespread decrease in Smad4 expression in mouse NK cells within CRC tumor TME." (PMID 39439794, 2024).